INS (insulin)
Diseases named in the same sentence as INS in open-access papers (continued):
Sharing a sentence is not in itself a finding about the gene and the disease.
type 2 diabetes (continued). "Randomized open-label trials comparing exenatide with insulin glargine or biphasic insulin aspart, combined with metformin and a sulfonylurea in patients with poorly controlled type 2 diabetes, demonstrated similar HbA1C reductions of -0.89 to -1.1% in the exenatide and insulin groups." (PMID 27713388, 2010). "Thus, synthetic PPARγ agonists, the thiazolidinediones (TZDs), are used in type 2 diabetes therapy as insulin sensitizers." (PMID 21057731, 2010). "Insulin introduction may be delayed in type 2 diabetes, and patients may under-dose insulin to avoid weightgain." (PMID 20843379, 2010). "A potential limitation of our findings is that this was an exploratory pilot study to evaluate the protective effects on the β cell by initiating basal insulin therapy with metformin in individuals with type 2 diabetes, pretreated with OADs (sulfonylurea in combination with metformin)." (PMID 20415692, 2010). "In another age-related disease, adult onset diabetes, defective insulin signaling through the insulin-PI3K-Akt pathway, which is upstream of mTOR, is well-established, although inhibition of this same pathway is known to extend lifespan in yeast and C. elegans models." (PMID 20862226, 2010). "Hypoinsulinemia in later stage leads to insulin insensitivity- a feature of type 2 diabetes." (PMID 20828387, 2010). "A single centre open label, randomized, two period cross over, isoglycemic glucose clamp study has been performed on 10 male insulin-naïve patients with type 2 diabetes who received 300 units of oral insulin and 15 units of human regular insulin on two separate days." (PMID 21059246, 2010). "In this content, one should recognize that physical activity, which can improve insulin sensitivity, was shown to prevent the development of cardiovascular diseases in type 2 diabetes and can improve diastolic function and exercise capacity in subjects with diastolic heart failure." (PMID 20950415, 2010). "Prospective studies show that many insulin resistant individuals are capable of maintaining euglycemia via compensatory responses, but that β-cell dysfunction and reduced β-cell mass are characteristics of those that develop type 2 diabetes." (PMID 20231880, 2010). "Thus, whilst pharmacological levels of GLP-1 or its DPP-IV resistant analogues undisputedly promote insulin secretion in type-2 diabetic patients, raising GIP levels is widely reported to be ineffective." (PMID 20204054, 2010). "Therefore, it is well known that the inhibition of the serine protease DPP-IV in type 2 diabetes treatment prevents its activation of insulin-releasing peptide hormones." (PMID 20652060, 2010). "The purpose of this project was to explore the potential of using a virtual world platform for medical education through the development of a one-hour, interactive seminar for postgraduate primary care physicians on the topic of insulin therapy for type 2 diabetes." (PMID 20097652, 2010). "But whether THADA has similar effect on beta cell and how it participates in the pathogenesis of type 2 diabetes and insulin secretion is still unknown." (PMID 19862325, 2009). "In addition, the user can learn that this interaction is involved in several biological processes together, because the interacting proteins have several pathways such as insulin signalling, type II diabetes, and DLPRA in common." (PMID 19594875, 2009). "As recent studies point towards a role for Wnt signaling in the pathogenesis of type 2 diabetes, we hypothesized that activation of Wnt signaling could play a crucial role in muscle insulin sensitivity." (PMID 20041157, 2009). "Interestingly however, the serum insulin levels of Nscl-2 mutant mice were virtually normal while ob/ob mice, which are a model of Type II diabetes, showed a massive increase in serum insulin concentrations." (PMID 19436734, 2009).
type 2 diabetes (continued). "Interestingly, PTHrP showed a positive correlation with insulin levels only among healthy individuals presumably due to defective glucose stimulated insulin secretion known to occur in type 2 diabetics." (PMID 19727413, 2009). "Insulin represents the cornerstone of care for achieving this target in patients with type 1 diabetes, and is also indicated in type 2 diabetes patients with suboptimal glycaemic control despite increasingly aggressive therapy with oral antidiabetic drugs (OADs) in addition to lifestyle changes." (PMID 19152692, 2009). "Based on these observations, we sought to investigate the impact of unsaturated fatty acids such as oleic acid in the presence of TNF-α in terms of insulin production, the molecular mechanisms involved and the in vivo effect of a diet high in oleic acid on a mouse model of type II diabetes, KKAy." (PMID 19558671, 2009). "The β-cell mitochondria are key regulators of glucose stimulated insulin secretion, and several mitochondrial pathways are disabled in type 2 diabetes (T2DM), e.g. the glucose induced hyperpolarization of the mitochondrial membrane and the raise in the ATP/ADP ratio at high glucose." (PMID 19197367, 2009). "This article presents a detailed description of a cluster RCT with the aim to investigate the effects of a patient-centred internet programme supporting self-titration of insulin therapy in type 2 diabetes patients compared with standard-of-care physician-driven insulin titration." (PMID 19508712, 2009). "Both type 1 diabetes (i.e. insulin dependent) and type 2 diabetes (i.e. not-insulin dependent) are associated to vascular events, in particular if glycated haemoglobin is higher than 7.0%." (PMID 19558686, 2009). "Emerging data support the hypothesis that in the particular case of young healthy insulin resistant offspring of parents with type 2 diabetes, alteration in mitochondrial activity would be partly inherited." (PMID 19333447, 2009). "The fact that pioglitazone is used to treat type 2 diabetes by regulating insulin sensitivity, may suggest that some of the protective effects of this drug in PD may be due to its ability to regulate insulin signaling, glucose metabolism or lactate production." (PMID 27713238, 2009). "Indeed, islets from patients with type 2 diabetes exhibit low ATP content and a blunted glucose-stimulated insulin secretion (GSIS) and increased mitochondrial volume, together implicating a role for mitochondria in the pathogenesis of β-cell dysfunction." (PMID 19956695, 2009). "The United Kingdom Prospective Diabetes Study (UKPDS) demonstrated that intensive blood glucose control with insulin or sulphonylurea in type 2 diabetic patients had only a limited effect on the incidence of cardiovascular events, indicating the necessity for new treatment strategies." (PMID 19635160, 2009). "Therefore, this retrospective analysis was performed to evaluate the effect of switching from premix to a glargine-based regimen on glycaemic control, body weight and insulin use in patients with type 1 or type 2 diabetes in a daily practice setting." (PMID 19220880, 2009). "Conversely, the ability to stimulate both the insulin and IGF-1 receptors may broaden the applicability of insulin in different wound conditions, particularly when one receptor may be missing or dysfunctional (e.g. type II diabetes)." (PMID 19134226, 2009). "In the Inter99 study the type 2 diabetes risk alleles in the region between the CDC123 and the CAMK1D and in the TSPAN8 locus associated with a range of OGTT-based surrogate measures of serum insulin release." (PMID 19789630, 2009). "Insulin therapy, whether a once-daily regimen with basal insulin or premixed insulin, is appropriate as an initial therapy for type 2 diabetes." (PMID 19573240, 2009).
type 2 diabetes (continued). "In the initial GWA meta-analysis the JAZF1 variant showed the strongest association with type 2 diabetes and the same variant has subsequently shown association with decreased BIGTT-AIR an estimate of serum insulin release following an OGTT in middle-aged Danes." (PMID 19789630, 2009). "In addition, a decrease in mitochondrial content and function has been described in the skeletal muscle of obese, insulin resistant and type 2 diabetic patients compared to healthy individuals." (PMID 19333447, 2009). "In everyday practice, patients with type 1 or type 2 diabetes inadequately controlled by premix insulins experienced significant improvement in glycaemic control over 12 months after switching to a glargine-based insulin regimen." (PMID 19220880, 2009). "Diabetes type 2 is now a global health problem, characterized of both insulin resistance and impaired insulin response to glucose, defects that are regarded multifactorial in origin and are considered a result of both environmental and undefined genetic factors." (PMID 18478125, 2008). "Alles stated that according to his experiences, Rosmary-ODB 5× per week within one months and 3× per week for two month may heal patients with type 2 diabetes (non-insulin dependent)." (PMID 19055811, 2008). "The reduced oxidative activity could also be a result of a sedentary lifestyle, and no data on correlations between changes in oxidative capacity and insulin sensitivity following exercise in type 2 diabetes have been published." (PMID 18371210, 2008). "These drugs are used as insulin sensitizers in the treatment of type II diabetes." (PMID 18645611, 2008). "However, most patients with type 2 diabetes will eventually require treatment with insulin due to the progressive decline of β-cell function, insulin resistance, and glucotoxicity that occur with the disease." (PMID 18279520, 2008). "In a mouse study aiming to understand why long-term treatment for type 2 diabetes with sulfonylureas eventually fails, Colin Nichols and Maria Remedi suggest that slow restoration of insulin secretion may be possible after a drug-resting period." (PMID 18959471, 2008). "Increasing evidence suggests that PPARGC1A is involved in the pathogenesis of type 2 diabetes by playing a pivotal role in the control of genetic pathways that result in homeostatic glucose utilization in liver and muscle, beta cell insulin secretion and mitochondrial biogenesis." (PMID 18523557, 2008). "The increase in severe episodes with duration of treatment has been confirmed by a UK-based retrospective study of 215 insulin-treated patients with Type 2 diabetes, which revealed that 15% had experienced severe hypoglycaemia in the preceding year (60 episodes in 32 people)." (PMID 18215172, 2008). "However, leaving type 2 diabetes untreated, hyperglycemiarequires exogenous insulin inputs like the type 1 diabetic therapy." (PMID 18437199, 2008). "Indications for insulin therapy in patients with type 2 diabetes." (PMID 19902051, 2008). "In agreement with these functional features, the presence ofanti-CD38 autoantibodies in type 2 diabetic patients was associated withsignificantly higher levels of fasting plasma C-peptide and insulin, ascompared with anti-CD38 negative subjects." (PMID 19300526, 2008). "In contrast to true Type 1 diabetics who produce insufficient insulin and true Type 2 diabetics who are unable to effectively use the insulin they produce, Type 3 diabetics are responding to environmental triggers that affect blood sugar readings and blood viscosity." (PMID 18568931, 2008). "In a review of medication–adherence literature for patients with type 2 diabetes, Rubin concluded that the adherence rate for oral antihyperglycaemic medication was approximately 65–85%, and insulin adherence may be slightly lower." (PMID 18393965, 2008). "Many patients with type 2 diabetes require insulin to maintain glycaemic control." (PMID 19143853, 2008).
type 2 diabetes (continued). "However, other work has shown that physician attitudes are closely linked to behaviour, leading us to assume that many PCPs delay the prescribing of insulin to patients with type 2 diabetes." (PMID 18393965, 2008). "This suggests that its main mechanism of action may not be potentiation of insulin release from pancreatic β-cells and therefore the drug could be effective in insulin independent, type II diabetes mellitus also." (PMID 20040954, 2008). "For example, systematically titrating bedtime basal insulin that had been added to oral therapy was shown to safely achieve an A1C of 7.0% in a majority of patients with type 2 diabetes whose A1C had been 7.5% to 10.0% while they were receiving oral agents alone." (PMID 18279520, 2008). "Our first paper, the first part ofthe survey, mostly spent its pages on the background of insulin-dependentdiabetes therapy, such as, description of type 1 and type 2 diabetes, theinsulin functionality, and medical devices involved in the insulin-dependenttherapy." (PMID 18566688, 2008). "An analog of amylin, a pancreatic peptide secreted by β cells in response to meals, pramlintide used in insulin-treated patients with type 1 diabetes and type 2 diabetes reduces PPG excursions, lowers A1C levels another 0.4% to 0.6%, increases satiety, and decreases food intake." (PMID 18279520, 2008). "The mechanisms by which TZDs exert their insulin sensitizing action in skeletal muscle of type 2 diabetic patients are not yet fully understood, but may include increased downstream insulin receptor signaling and enhanced fatty acid uptake and oxidation." (PMID 18560589, 2008). "Yet, a two-year prospective descriptive study showed that insulin therapy initiation in relatively asymptomatic type 2 diabetes patients who were treated with diet and/or hypoglycaemic agents resulted in improved glycaemia control, without major adverse influences on patients' quality of life." (PMID 17727695, 2007). "Insulin use in secondary care for type 2 diabetes has risen in the last 5–10 years, but in primary care the initiation of insulin has risen more slowly, and has only accelerated in the last 2 years following the use of once daily long acting insulin with the simultaneous use of oral agents." (PMID 17678547, 2007). "This study will extend the current data on CyclosetTM safety, tolerability and efficacy in individuals with type 2 diabetes to include its effects in combination with thiazolodinediones, insulin secretagogues, metformin, alpha-glucosidase inhibitors and exogenous insulin regimens." (PMID 17592632, 2007). "The questionnaire aims at exploring motivation, fears, and barriers towards insulin injection therapy (type 2 diabetes patients treated with oral hypoglycaemic agents) or towards intensifying injections (type 1 or type 2 diabetic patients already treated with insulin injection)." (PMID 17727695, 2007). "Patients with type 2 diabetes who fail to respond adequately to oral antidiabetic medications (OADs) or whose glycemic control worsens despite using recommended combinations of OADs often start insulin therapy." (PMID 17683531, 2007). "However, the decreased insulin in that study points to impaired beta cell function in the pancreas, as found in type 1 diabetes or later in the course of type 2 diabetes." (PMID 17589594, 2007). "Approximately 12% of all individuals with type 2 diabetes received insulin in 2001." (PMID 17164006, 2006). "Our long-term objective has been to develop a diet that does not require weight loss, oral agents, or insulin, but still controls blood glucose in people with type 2 diabetes." (PMID 16556307, 2006). "Thus, an appreciation of the mechanisms regulating β cell function and insulin secretion is crucial towards understanding the pathogenesis of type 2 diabetes." (PMID 16464129, 2006).
type 2 diabetes (continued). "The purpose of this study was to examine the association between race/ethnicity and control of cardiovascular disease risk factors, adjusted for socioeconomic, clinical, and behavioral factors, in a large cohort of insulin-treated veterans with type 2 diabetes." (PMID 16716235, 2006). "However, when subjects with type 2 diabetes ingested protein, the insulin concentration increased markedly." (PMID 16556307, 2006). "No variant was associated with type 2 diabetes, and no variant altered insulin secretion or insulin sensitivity." (PMID 16869959, 2006). "However, the addition of butter clearly stimulated an increase in insulin concentration in people with type 2 diabetes." (PMID 16556307, 2006). "In a worst case scenario, long-term inhibition of IGF-IR could induce type I and type II diabetes by inhibiting insulin secretion and insulin action, respectively." (PMID 16450000, 2006). "Consequently, blood glucose levels increase and more insulin is released, producing hyperinsulinemia, which manifests early in type 2 diabetes." (PMID 16393666, 2006). "Our objective has been to develop a diet for people with type 2 diabetes that does not require weight loss, oral agents, or insulin, but that still controls the blood glucose concentration." (PMID 16556307, 2006). "In a 5-week crossover feeding study, 8 men with type 2 diabetes had greater improvement in fasting glucose, 24-hour glucose area-under-the-curve (AUC), 24-hour insulin AUC, and glycohemoglobin while on the low-carbohydrate diet than when on a eucaloric low-fat diet." (PMID 16318637, 2005). "This is in contrast to a recent report that fasting tHcy concentrations were closely and independently associated with estimated glomerular filtration rate, but not with serum creatinine, in groups of patients with type 1 and type 2 diabetes undergoing intensive insulin treatment." (PMID 15918903, 2005). "Because glucose is the major insulin secretagogue carbohydrate reduction would be expected to be beneficial in type 2 diabetes and the use of such diets has been summarized by Arora & McFarlane although official recommendations generally continue to recommend low fat and high carbohydrate intake." (PMID 16232315, 2005). "To test these hypotheses, we monitored insulin secretion and islet pHi in two mouse models of type 2 diabetes." (PMID 16336655, 2005). "However, the proportion of type 2 diabetics treated by diet alone fell between 1994 and 2001 (from 38.2% to 33.0%), while those treated with any insulin (13.2% to 15.1%) and oral agents only (48.6% to 51.8%) both increased." (PMID 15784133, 2005). "The aim of the present study was to evaluate, by heart rate variability with 24-hours ECG Holter registration, the autonomic activity and circadian autonomic rhythm in offspring of type 2 diabetic subjects and to evaluate the possible impact of sympathetic activity on insulin resistance." (PMID 16197556, 2005). "Defective insulin secretion is a key defect in the pathogenesis of type 2 diabetes (T2DM)." (PMID 16229747, 2005). "However, there was a relatively large increase in insulin concentration in the subjects with type 2 diabetes." (PMID 15507157, 2004). "β-Cell transplantation, as well as approaches that replenish or preserve the endogenous β-cell mass, may facilitate the treatment of type 2 diabetes in patients requiring exogenous insulin." (PMID 12745664, 2003). "Insulin secretion declines progressively before and during thecourse of type 2 diabetes." (PMID 12458655, 2002). "People with either type 1 or type 2 diabetes generally are treated with insulin injections or—for people with type 2—with medications that stimulate the body’s own insulin production (e.g., a class of medications called sulfonylureas or an agent called repaglinide)." (PMID 15706798, 1998).